ADIPOQ (adiponectin, C1Q and collagen domain containing)
Diseases named in the same sentence as ADIPOQ in open-access papers (continued):
Sharing a sentence is not in itself a finding about the gene and the disease.
metabolic syndrome (46 papers, 2011 to 2026). A cluster of metabolic risk factors for CARDIOVASCULAR DISEASES and TYPE 2 DIABETES MELLITUS. "Nonetheless, the ‘C,T,T’ haplotype has been associated with risk to metabolic syndrome in a cohort of Sudanese patients, highlighting these ADIPOQ SNPs as possible targets in further studies." (PMID 41602445, 2026). "This narrative review examines current evidence on the relationship between adiponectin, ADIPOQ gene variants, and metabolic syndrome." (PMID 40565591, 2025). "Adiponectin is an adipose-specific protein, encoded by ADIPOQ, which blood concentration decreases with obesity, metabolic syndrome, or T2D." (PMID 38491190, 2024). "ADIPOQ has been identified as candidate gene for the metabolic syndrome and T2DM by genome wide associated study." (PMID 37024992, 2023). "ADIPOQ located on chromosome 3q27 is a susceptibility locus for metabolic syndrome and is composed of three exons and two introns spanning a 17 kb region." (PMID 36094942, 2022). "Meanwhile, dyslipidemia associated with decreased ADIPOQ expression in EAT and PVAT, LEPR in EAT, and IL6 in PVAT." (PMID 36157437, 2022). "investigate the association between the +45T > G variant of the ADIPOQ gene and the metabolic syndrome (MS) in patients with sickle cell trait (SCT)." (PMID 33748495, 2021). "One of the candidate genes for DKD is adiponectin (ADIPOQ), which has been indicated to be linked to susceptibility to cardiovascular disease, metabolic syndrome, and T2DM." (PMID 32685557, 2020). "Adiponectin, adipocytokine encoded by ADIPOQ, is central to insulin sensitivity and resistance and other metabolic syndrome traits in diverse populations." (PMID 25121131, 2014). "In line with plasma levels of adiponection, the ADIPOQ gene has been identified as a susceptibility locus for the metabolic syndrome, T2DM, and cardiovascular disease." (PMID 24414038, 2014). "The ADIPOQ gene is located on human chromosome 3q27, where a region composed of three exons that span 17 kb, identified as a susceptibility locus for metabolic syndrome and T2DM, has been reported." (PMID 25561226, 2014). "In the Genetic Epidemiology of Metabolic Syndrome Study, the SNPs most strongly associated with adiponectin were rs3774261 and rs6773957 in ADIPOQ gene in Northern and Western European populations." (PMID 23590551, 2013). "ADIPOQ located on chromosome 3q27 has been identified as a susceptibility locus for metabolic syndrome and T2DM, and is composed of three exons and two introns spanning a 17 kb region." (PMID 23826253, 2013). "A number of studies have reported that polymorphisms in the ADIPOQ gene are associated with metabolic syndrome in Chinese Han populations." (PMID 23593121, 2013). "The association of ADIPOQ variants and variable subtypes of hypertension and metabolic syndrome among study subjects in replication study." (PMID 21637762, 2011). "Adiponectin is encoded by the ADIPOQ gene on chromosome 3q27, a region identified as susceptibility locus for the metabolic syndrome and T2DM by genome wide scans." (PMID 21219602, 2011). "Adiponectin; metabolic syndrome; sickle cell trait; rs 2241766; +45T > G variant in ADIPOQ gene." (PMID 33748495, 2021). "Association between ADIPOQ polymorphisms and metabolic syndrome risk." (PMID 30265726, 2018). "In conclusion, the results of this study indicate that FABP2, ANP and ADIPOQ gene variants are associated with metabolic syndrome or its components in Afro-Caribbeans and suggest a cumulative effect of these variants on the risk of metabolic syndrome and hypertriglyceridemia." (PMID 27684940, 2016). "Several SNPs inside the ADIPOQ gene have been associated with adiponectin serum levels, body adiposity and other metabolic alterations, rendering it a potential player in obesity and metabolic syndromes." (PMID 27703473, 2016).
metabolic syndrome (continued). "In previous studies, the rs1501299 polymorphism of the ADIPOQ gene has been correlated with T2DM, cardiovascular diseases, metabolic syndrome, hepatocellular carcinoma, and endometrial cancer." (PMID 39202535, 2024). "Background and Aims: The present study was designed to investigate SNP rs17300539 in the ADIPOQ gene and its relationships with obesity, metabolic syndrome (MS), and serum circulating adiponectin." (PMID 38140287, 2023). "In the current study, the presence of dyslipidemia in CAD patients correlated with decreased ADIPOQ expression in EАT and PVАT." (PMID 36157437, 2022). "Previous studies demonstrated association of functional ADIPOQ gene variants with altered circulating adiponectin concentrations, and with pregnancy complications, including GDM, metabolic syndrome, and preeclampsia (PE)." (PMID 29559003, 2018). "It is well documented that lower plasma ADIPOQ levels were associated with obesity, T2DM, dyslipidemia and higher blood pressure." (PMID 23593121, 2013). "Our results demonstrated ADIPOQ as a pleiotropic locus for metabolic syndrome and its components in the Han Chinese population." (PMID 23593121, 2013). "On the other hand, we provided a druggable protein, ADIPOQ, for drug discovery and drug design for diabetic cures with dyslipidemia that might be interesting for pharmaceutical insight and drug design-based natural products." (PMID 37542207, 2023). "As specific to the intrauterine impact of maternal sleep, only animal studies were conducted and showed that the sleep fragmentation during the late gestation induced the offspring’s AdipoQ methylation modification along with the higher weight and other metabolic syndrome-like phenotypes." (PMID 35596190, 2022). "Several studies have found that multiple SNPs in the adiponectin gene (ADIPOQ) might be related to lipid levels and dyslipidemia." (PMID 35052501, 2022). "The area of chromosome 3q27 where the ADIPOQ gene is located has been identified by genome-wide linkage studies (GWLSs) to be a susceptibility locus for risk for the type 2 diabetes (T2DM), metabolic syndrome (MS) and cardiovascular disease." (PMID 21251282, 2011). "In addition, ADIPOQ and IL-6 could consider cut-point nodes and suitable proteins in the pathomechanism of T2D and dyslipidemia." (PMID 37542207, 2023). "However, it was found that hypertension, hyperglycemia, BMI, WC, serum TG, ADIPOQ rs2241766 (TG), and ADIPOQ rs1501299 (GT) can independently predict the occurrence of metabolic syndrome in healthy Sudanese adults when using multivariate logistic regression analysis." (PMID 37151957, 2023). "The aim of this study was to determine the levels of leptin (Lep) and adiponectin (AdipoQ) in patients with gout and its relationship with joint inflammatory data and/or with metabolic syndrome (MetS) variables, during 1 year follow-up." (PMID 26131838, 2015). "Underexpression of the adiponectin gene (ADIPOQ) and simultaneous upregulation of leptin (LEP) were detected in the analysis of the transcriptome from the adipocytes of patients with metabolic syndrome after coronary artery bypass grafting." (PMID 32121175, 2020). "The ADIPOQ gene is located nearby the IGF2BP2 (insulin-like growth factor 2 mRNA-binding protein 2) and AOMS1 (abdominal obesity-metabolic syndrome QTL 1) genes on chromosome 3q27 (based on Ensembl database)." (PMID 21251282, 2011). "In addition, CCQS-specific and QSBS-specific genes were also enriched in metabolic Syndrome and cerebrovascular disease, respectively, in which Syndrome-specific DPs involved in the diseases were PON1 and ADIPOQ for CCQS, APOE and APOA1 for QSBS." (PMID 34702323, 2021). "ADIPOQ is considered a gene for T2DM and metabolic syndrome." (PMID 24414038, 2014).
breast cancer (32 papers, 2012 to 2025). A primary or metastatic malignant neoplasm involving the breast. "The authors reported that a lower ADIPOQ expression was associated with more aggressive phenotypes of breast cancer, and higher ADIPOR1 expression was associated only with larger tumours." (PMID 41456223, 2025). "Many studies have reported that decreased expression of ADIPOQ is associated with an increased risk of various types of cancer, including colorectal, endometrial, gastric, liver, and breast cancer, among others." (PMID 39684225, 2024). "As far as we know, we, for the first time, meta-analyzed the association between ADIPOQ gene and breast cancer." (PMID 37274250, 2023). "Taken together, we found, in this meta-analysis, that LEP gene rs7799039 and ADIPOQ gene rs1501299 were two promising candidate loci in predisposition to breast cancer risk." (PMID 37274250, 2023). "The aim of this meta-analysis was to examine the association of 5 genetic alterations in LEP and ADIPOQ genes, as well as their receptor-encoded genes, with breast cancer risk and circulating leptin levels." (PMID 37274250, 2023). "In this study, we aimed to perform a meta-analysis to evaluate the association of genetic alterations in LEP and ADIPOQ genes, as well as their receptor-encoded genes with risk for breast cancer." (PMID 37274250, 2023). "In conclusion, through a comprehensive analysis of 33 publications, we found that LEP gene rs7799039 and ADIPOQ gene rs1501299 were two promising candidate loci in predisposition to breast cancer risk." (PMID 37274250, 2023). "Circulating ADIPOQ levels decrease with increasing BMI and are associated with increased breast cancer risk." (PMID 35846306, 2022). "In relation to the ADIPOQ gene, the heterozygous CT genotype in rs6773957 (C/T) was negatively associated with breast cancer risk among individuals with under/normal weight by roughly 60% in model." (PMID 34367982, 2021). "Of these studies, one study was conducted in AA women reporting that only ADIPOQ rs1501299 was associated with increased breast cancer incidence." (PMID 34367982, 2021). "Adipose tissues secrete ADIPOQ and LEP-ADIPOQ axis has been well implicated in breast cancer tumorigenesis." (PMID 25923423, 2015). "In addition, genetic variations in the leptin-coding genes LEP and ADIPOQ have been associated with elevated breast cancer risk." (PMID 39251829, 2024). "We thereby hypothesize that genes coding leptin (LEP) and adiponectin (ADIPOQ) and their receptors are promising candidates in predisposition to breast cancer risk." (PMID 37274250, 2023). "Additionally, in subcutaneous adipose-associated cancers such as breast cancer and melanoma, the ADIPOQ+Adi subtype was associated with poor survival outcomes." (PMID 37454080, 2023). "Importantly, we found that LEP gene rs7799039 and ADIPOQ gene rs1501299 were two promising candidate loci in predisposition to breast cancer risk." (PMID 37274250, 2023). "Under dominant mode, the protective effects of LEP gene rs7799039 GG plus GA genotypes and LEPR gene rs1137100 AA plus AG genotypes on breast cancer risk dwindled, and the risk conferred by ADIPOQ gene rs1501299 TT plus TG genotypes was enhanced, with OR of 1.41 (95% CI: 1.06 to 1.88)." (PMID 37274250, 2023). "Our findings supported this hypothesis by showing that LEP gene rs7799039 and ADIPOQ gene rs1501299 were two promising breast cancer-susceptibility loci." (PMID 37274250, 2023). "To test this hypothesis, we conducted a meta-analysis on genetic alterations in LEP and ADIPOQ genes as well as their receptor-encoded genes by pooling published summary data, aiming to evaluate their association with risk for breast cancer, as well as circulating leptin and adiponectin levels." (PMID 37274250, 2023). "However, it is worth mentioning that another event increasing the incidence of breast cancer may come from ADIPOQ and/or ADIPOR1 single nucleotide polymorphisms." (PMID 37240258, 2023).
breast cancer (continued). "Circulating levels of AdipoQ are significantly decreased in breast cancer, endometrial cancer, ovarian cancer, prostate cancer and other tumors." (PMID 39349421, 2024). "This study was aimed at investigating the expression of survivin variants S-WT, S-2B, and S-ΔEx3, as well as adipokines LEP and ADIPOQ in breast cancer." (PMID 35342410, 2022). "Exosomal transfer of miR-9-5p augmented the resistance of breast cancer cells to tamoxifen by inhibiting ADIPOQ." (PMID 36703740, 2022). "A recent study found that ADIPOQ is negatively regulated by miR-9-5p, which plays a role in the sensitivity of breast cancer cells to tamoxifen." (PMID 36114448, 2022). "Lower expression levels of five hub gens, including IGF1, LEP, ADIPOQ, NR3C1, and PPARG, were determined and were remarkably associated with poorer OS and BCSS among breast cancer patients." (PMID 35317079, 2022). "ADIPOQ/adiponectin is an abundant adipocytokine secreted by AT and adipocytes of breast cancer tissue and possesses insulin sensitizing, anti-inflammatory function, and antiatherogenic performances." (PMID 35701840, 2022). "A study focusing on the molecular mechanisms ADIPOQ participated in has revealed that ADIPOQ induces cytotoxic autophagy in breast cancer cells through STK11/LKB1-mediated activation of the AMPK-ULK1 axis." (PMID 33717664, 2021). "In vitro studies have shown ADIPOQ stimulates growth in ER+ breast cancer cells and inhibits cellular proliferation in ER− breast cancer cells." (PMID 32046756, 2020). "We showed that two functional polymorphisms of ADIPOQ, and one functional polymorphism which has been shown to alter mRNA levels of ADIPOR1 was significantly associated with risk of breast cancer." (PMID 22295251, 2012). "Although the significant association between LEP, LEPR and ADIPOQ genes and breast cancer risk, we did not notice remarkable differences in circulating leptin levels across genotypes of their genetic alterations." (PMID 37274250, 2023). "Therefore, further research and exploration are necessary to fully understand the role of ADIPOQ and AdipoR1/2 in breast cancer." (PMID 37454080, 2023). "In particular, rs1501299 in the adiponectin gene (ADIPOQ) was associated with an increased risk of breast cancer in some studies, but not in others." (PMID 34367982, 2021). "The molecular mechanisms underlying the association between increased adiposity and aggressive breast cancer phenotypes remain unclear, but likely involve the adipokines, leptin (LEP) and adiponectin (ADIPOQ), and their receptors (LEPR, ADIPOR1, ADIPOR2)." (PMID 32046756, 2020). "However, evidence suggests that there is a dichotomy observed in the relationship between ADIPOQ and breast cancer progression by ER status." (PMID 32046756, 2020). "Our overarching hypothesis was that higher IHC expression of LEP, LEPR, ADIPOQ, ADIPOR1, and ADIPOR2 within the breast tumor microenvironment is associated with breast cancer aggressiveness, but we generally observed the opposite." (PMID 32046756, 2020). "The relationship between adiposity and breast cancer might be explained partly by biological effects of the adipokines, ADIPOQ, and LEP, which are secreted by adipocytes." (PMID 32046756, 2020). "In tamoxifen-resistant breast cancer cells, exosomes released by these cells might negatively regulate ADIPOQ expression in recipient cells, rendering more cancer cells tolerant to chemotherapy drugs upon interaction with surrounding drug-sensitive tumor cells." (PMID 38001753, 2023). "Besides, the autophagy activator adiponectin ADIPOQ and 2-aminonicotinonitrile compound (w09) significantly inhibit breast cancer growth by stimulating autophagy through the serine/threonine kinase 11 (STK11)-AMPK-ULK1 and EGFR-mediated RAS-RAF1-MAP2K-MAPK1/3 pathway, respectively." (PMID 35725836, 2022).
breast cancer (continued). "Additionally, the resistance of breast cancer cells to the treatment agent, tamoxifen, may be facilitated by an exosomal transfer of miR-9-5p and negative regulation of ADIPOQ." (PMID 36555323, 2022). "Oncoprint analysis revealed genetic alterations in FABP4 (14%), ADIPOQ (2.9%), PPARG (2.8%), PPARGC1A (1.5%), CD36 (1.7%), and CREBBP (11%) in patients with breast cancer in the TCGA study." (PMID 36114448, 2022). "Subsequently, 10 top hub genes were identified and five (IGF1, ADIPOQ, PPARG, LEP, and NR3C1) significantly correlated with worse OS and BCSS on response to trastuzumab in breast cancer patients." (PMID 35317079, 2022). "Patients with breast cancer who had low mRNA levels of FABP4, ADIPOQ, PPARG, and PPARGC1A had lower overall survival rates than those with high mRNA levels, which was supported by the overall survival related to DNA methylation." (PMID 36114448, 2022). "Oncoprint analysis showed genetic alterations in FABP4 (14%), ADIPOQ (2.9%), PPARG (2.8%), PPARGC1A (1.5%), CD36 (1.7%), and CREBBP (11%) in patients with breast cancer in a TCGA study." (PMID 36114448, 2022). "This study explored the potential targets of RGZ as antiangiogenic agents in breast cancer therapy and highlighted FABP4, ADIPOQ, PPARG, PPARGC1A, CD36, and CREBBP as potential targets of RGZ." (PMID 36114448, 2022). "Patients with breast cancer who had low mRNA expression levels of FABP4 (log-rank P = 0.012), ADIPOQ (log-rank P = 0.01), and PPARG (log-rank P = 0.00013) had worse OS than those with high mRNA levels." (PMID 36114448, 2022). "Oncoprint analysis revealed genetic alterations in FABP4 (14%), ADIPOQ (2.9%), PPARG (2.8%), PPARGC1A (1.5%), CD36 (1.7%), and CREBBP (11%) in patients with breast cancer in a TCGA study." (PMID 36114448, 2022). "DNA methylation analysis revealed that the predictive significance of FABP4, ADIPOQ, PPARG, PPARGC1A, CD36, and CREBBP in a specific CpG was significant in the emergence of breast cancer." (PMID 36114448, 2022). "We demonstrated a heatmap and prognostic value of DNA methylation clustering of the expression levels of FABP4, ADIPOQ, PPARG, PPARGC1A, CD36, and CREBBP in breast cancer." (PMID 36114448, 2022). "We used immunohistochemistry (IHC) to assess LEP, LEPR, ADIPOQ, ADIPOR1, and ADIPOR2 expression in breast tumor tissue microarrays among a sample of 720 women recently diagnosed with breast cancer (540 of whom self-identified as Black)." (PMID 32046756, 2020). "AdipoQ is potentially able to regulate autophagy through AMPK, whose activation has been observed in breast cancer cells." (PMID 25317422, 2014). "Furthermore, it has been described that ADIPOQ and their receptor are expressed in the TME of breast cancer." (PMID 41456223, 2025). "Finally, spots in the fourth cluster coexpress adipocyte markers (ADIPOQ, PLIN1, CIDEC) reflecting adipocyte-rich stroma that lead to microvasculature in breast cancer." (PMID 41249066, 2025). "Therefore, we considered IGF1, LEP, ADIPOQ, NR3C1, and PPARG as potential predictors for the poor prognosis of patients with breast cancer." (PMID 35317079, 2022). "Analysis of the prognostic value related to TR expression showed that patients with breast cancer with low mRNA expression levels of FABP4 (log-rank P = 0.012), ADIPOQ (log-rank P = 0.01), PPARG (log-rank P = 0.00013), and PPARGC1A (log-rank P = 0.02) had worse OS than those with high mRNA levels." (PMID 36114448, 2022). "Furthermore, the low expression levels of ADIPOQ (HR = 0.416, p < 0.01), IGF1 (HR = 0.458, p < 0.05), LEP (HR = 0.527, p < 0.05), NR3C1 (HR = 0.457, p < 0.05), and PPARG (HR = 0.491, p < 0.05) were notably related to the poorer BCSS of breast cancer patients with tumor pathological stages III–IV." (PMID 35317079, 2022). "The mRNA levels of FABP4, ADIPOQ, PPARG, CD36, and PPARGC1A were significantly lower in patients with breast cancer than in those without breast cancer." (PMID 36114448, 2022).
breast cancer (continued). "The mRNA expression levels of FABP4, ADIPOQ, PPARG, CD36, and PPARGC1A were significantly lower in patients with breast cancer, whereas the mRNA levels of CREBBP were not different between patients with breast cancer and normal breast tissues." (PMID 36114448, 2022).